TSPAN12 (tetraspanin 12)
Diseases named in the same sentence as TSPAN12 in open-access papers (continued):
Sharing a sentence is not in itself a finding about the gene and the disease.
tumor (14 papers, 2016 to 2024). "For example, in breast cancer, Tspan12 has a pro-apoptotic function, as it significantly reduced primary tumor xenograft growth, while increasing tumor apoptosis." (PMID 38649381, 2024). "Tspan12 removal reduces tumor growth and promotes apoptosis, altering the expression of β-catenin-regulated genes." (PMID 38649381, 2024). "Report suggested that TSPAN12 knockdown H1299/shTSPAN12 cells were injected in nude mice, resulting in significantly increased tumor size." (PMID 36620544, 2022). "Recent studies have demonstrated that ECM1, ENPP1, TSPAN12 were involved in tumor invasion and metastasis." (PMID 35645555, 2022). "Our results showed that silencing the expression of TSPAN12 antagonized the enhancement of the in vivo HCC tumor growth induced by RNF152 depletion." (PMID 33602225, 2021). "TSPAN12 can promote tumor cell proliferation and colony formation, and high expression of CD9 is considered to be related to lymph node metastasis." (PMID 32694936, 2020). "Additionally, the expression of the TSPAN12 gene, which encodes the tetraspanin-12 protein, is regulated by miR-495, leading to the inhibition of SCLC tumour growth." (PMID 38203731, 2023). "Liang G. and colleagues found that TSPAN12 could inhibit tumor growth of non-small lung cancer cells." (PMID 36941633, 2023). "For example, miR-196b-5p was reported to enhance cell migration, proliferation, and tumor growth by affecting the tumor suppressors, TSPAN12, and GATA6 while increased miR-196b-5p expression in NSCLC was partly monitored by hypomethylation of its promoter section." (PMID 35514980, 2022). "In comparison, tetraspanin 12 (Tspan12, a paralogue of Tspan18), recently shown to be expressed in retinal vessels, was widely expressed in embryonic tissues as well as human tumor cell lines." (PMID 32694189, 2021). "Tspan12 removal also altered the expression of several genes regulated by β-catenin (CCNA1, CCNE2, WISP1, ID4, SFN, ME1), inhibiting alterations in tumor growth and metastasis." (PMID 38649381, 2024). "In this study, we uncovered a tumor suppressor role of RNF152 in HCC and found that RNF152 is down-regulated and essential to inhibit the proliferation and invasion of HCC via TSPAN12 degradation." (PMID 33602225, 2021). "miR-196b-5p downregulates the tumor suppressors, GATA6 and TSPAN12 expression." (PMID 36620544, 2022). "Importantly, silencing the expression of TSPAN12 antagonized the enhancement of the HCC cell growth, colony formation, and invasion in vitro as well as HCC tumor growth in vivo induced by RNF152 depletion." (PMID 33602225, 2021).
cancer (11 papers, 2015 to 2025). A tumor composed of atypical neoplastic, often pleomorphic cells that invade other tissues. "Cancer cells contact fibroblasts with tetraspanin 12 and transduce β-catenin signaling in CAFs, leading to the secretion of CXCL6, which promotes cancer invasion." (PMID 38730588, 2024). "Met, Tspan12, and Fam3c, which are located on DMs, facilitate cancer malignancies, and are correlated with poor prognosis." (PMID 29497033, 2018). "In particular, several tetraspanins, such as CD151, TSPAN12, and TSPAN8, among others, have been implicated in cancer initiation, progression and metastasis in mammals." (PMID 25978409, 2015). "TSPAN1, TSPAN3, TSPAN12, TSPAN31, CD82 and CD63 have also been reported to reduce chemosensitivity of cancer cells." (PMID 36941633, 2023). "However, the molecule expressed in cancer cells that binds to tetraspanin 12 on CAFs has not yet been identified." (PMID 38730588, 2024).
retinopathy (4 papers, 2022 to 2023). "FZD4-selective WNT surrogates also regulate BRB function in neonatal Tspan12−/− mice with partial rescue at 2–3 months of age28, and in postnatal oxygen-induced retinopathy models in WT mice." (PMID 37268690, 2023). "FEVR is an inherited retinal disorder characterized by incomplete retinal vascular development and secondary retinal changes, and has been reported to be associated with Wnt signaling genes (FZD4, TSPAN12, and NDP) polymorphism." (PMID 35022017, 2022).
colorectal (1 paper, 2020). "Additionally, the genes that were highly expressed in colorectal patients are TSPAN2, TSPAN5, TSPAN12, TSPAN28, TSPAN29, and TSPAN33." (PMID 32694936, 2020).
digestive system cancer (1 paper, 2024). A primary or metastatic malignant neoplasm involving any part of the digestive system. "Generally, the expression of CD9, CD151, Tspan1, Tspan5, Tspan8, Tspan12, Tspan15, and Tspan31 are upregulated, facilitating the migration and invasion of digestive system cancer cells." (PMID 38389703, 2024).
infection (1 paper, 2016). The state of being infected such as from the introduction of a foreign agent such as serum, vaccine, antigenic substance or organism. "The expression of FZD3, NHS, NOG and TSPAN12 differed significantly between the two pools of cells following infection." (PMID 26837541, 2016).
TSPAN12 also shares sentences with these, for which no sentence is quoted: alcohol dependence (1 paper); aniridia (1); autism spectrum disorder (1); Best vitelliform macular dystrophy (1); cerebral infarction (1); Coats disease (1); diabetic retinopathy (1); eye disorder (1); glaucoma (1); glioblastoma (1); hyperlysinemia (1); ischemia (1); liver cancer (1); lung adenocarcinoma (1); mesothelioma (1); microcephaly-lymphedema-chorioretinal dysplasia (1); optic atrophy (1); prion disease (1); prostate carcinoma (1); retinal (1); retinal vascular disorder (1); Stroke (1); Wagner syndrome (1).